ING3 (inhibitor of growth family member 3)
Diseases named in the same sentence as ING3 in open-access papers (continued):
Sharing a sentence is not in itself a finding about the gene and the disease.
colon carcinoma (7 papers, 2018 to 2025). "Overexpression of ING3 in colon cancer cell lines induces apoptosis and inhibits tumour growth, whereas downregulation of ING3 is associated with a poor prognosis in cutaneous melanoma." (PMID 33925563, 2021). "CASC7 inhibits the proliferation and migration of colon cancer cells via miR-21/ING3 axis, and it represses the proliferation of glioma cells via negatively regulating Wnt/β-catenin signaling pathway." (PMID 33231565, 2020). "Similarly to ING4, interaction with p21 and Bax was demonstrated for ING3 as well: it was shown that ING3 induced the expression of p21 and Bax which resulted in apoptosis and diminished cell proliferation as shown in the RKO colon carcinoma cell line." (PMID 31390718, 2019).
melanoma (7 papers, 2008 to 2025). A malignant, usually aggressive tumor composed of atypical, neoplastic melanocytes. "ING3 is downregulated in head and neck carcinoma, melanoma, and hepatocellular carcinoma, while ING4 is reduced in bladder and colorectal cancer." (PMID 34685579, 2021). "For example, when ING3 protein accumulates in the nucleus, it suppresses melanoma cell migration, invasion, and angiogenesis." (PMID 34685579, 2021). "This suggests that the expression of ING3 in the nucleus can be used as a basis for evaluating and predicting the prognosis of patients with primary melanoma." (PMID 33469513, 2020). "Early studies reported that, similar to ING1, ING3 functions as a type II tumor suppressor to regulate apoptosis and is downregulated in cancers such as melanoma and head and neck carcinoma." (PMID 28511652, 2017). "Nuclear localization of ING3 is required to suppress melanoma cell angiogenesis." (PMID 40329179, 2025). "It had been well demonstrated that ING3 might be a positive independent factor in melanoma, human primary hepatocellular carcinoma and head and neck cancer." (PMID 33469513, 2020). "Studies has shown that there might be a translocation of ING3 from nucleus to cytoplasm in melanoma." (PMID 33469513, 2020). "In contrast to previous studies in melanoma and hepatocellular carcinoma reporting reduced ING3 levels in aggressive cancers, our analyses of primary prostate tumors showed that high levels of ING3 predict poorer outcome in patients with low AR levels." (PMID 28511652, 2017). "In contrast to its putative role as a tumour suppressor, a correlation study showed that strong nuclear staining for ING3 was associated with significantly worse five-year disease-survival compared with negative-to-moderate nuclear ING3 staining in malignant melanoma." (PMID 31905726, 2019).
hepatocellular carcinoma (5 papers, 2017 to 2025). A malignant tumor that arises from hepatocytes. "Downregulation of ING3 expression at the mRNA level has been linked to human head and neck cancers and hepatocellular carcinoma, while reduced nuclear ING3 localization has been reported to be a key indicator of human cutaneous melanoma progression." (PMID 40149370, 2025). "Loss of heterozygosity (LOH) of the ING3 locus was also found in ameloblastoma, hepatocellular carcinoma, and colorectal cancer, supporting its tumour suppressor candidate gene status." (PMID 31905726, 2019). "Similarly, the expression of ING3 decreased in many tumors, including human cutaneous melanoma, human head and neck cancers and human primary hepatocellular carcinoma." (PMID 33469513, 2020). "ING3 has been linked to head and neck and hepatocellular cancers, although its status as a tumour suppressor has not been well established." (PMID 31905726, 2019).
gastric cancer (4 papers, 2012 to 2022). A primary or metastatic malignant neoplasm involving the stomach. "Studies have shown that ING3 regulates cell proliferation, apoptosis, and cell cycle arrest in gastric cancer by inactivating the PI3K/Akt pathway and promoting cell death." (PMID 35845928, 2022). "The growth and activity of gastric cancer cells were inhibited by the upregulated expression of the inhibitor of growth 3 (ING3) following treatment with propofol, and ING3 exerted an important role in propofol‐induced anti‐tumour effects." (PMID 32596964, 2020). "Furthermore, overexpression of ING3 in gastric cancer cells resulted in apoptosis with increased BAX and CASPASE-3 expression and down-regulated expression of the anti-apoptotic protein BCL2." (PMID 31905726, 2019). "Interestingly, the association of allelic loss and reduced expression of ING3 with head and neck cancers is reminiscent of a similar association in chromatin remodeling genes of the SWI/SNF complex in CSS with tumorigenesis and gastric cancer." (PMID 23300646, 2012).
head and neck cancer (4 papers, 2012 to 2025). A primary or metastatic malignant neoplasm affecting the head and neck. "In head and neck cancer, translocalization of ING3 affected tumorigenesis and cancer progression." (PMID 34063938, 2021).
head and neck squamous cell carcinoma (3 papers, 2013 to 2022). A squamous cell carcinoma that arises from any of the following anatomic sites: lip and oral cavity, nasal cavity, paranasal sinuses, pharynx, larynx, and salivary glands. "Downregulation of ING3 expression and its transfer to the cytoplasm can regulate cell cycle arrest, senescence, and apoptosis in head and neck squamous cell carcinoma." (PMID 35845928, 2022).
lymph node metastasis (2 papers, 2020 to 2023). "The results showed that high expression of ING3 was negatively associated with a more advanced TNM stage (III-IV vs. I-II) (OR=0.61, 95% CI: 0.43-0.86), lymph node metastasis (OR=0.67, 95% CI: 0.49-0.90) and disease-free survival (HR=0.63, 95% CI: 0.37-0.88)." (PMID 36845697, 2023). "The downregulated ING3 in nucleus was significantly correlated with clinicopathological characteristics including histological grade, lymph node metastasis, and the status of ER and PR." (PMID 33469513, 2020). "In addition, we also found that the expression of nuclear ING3 was correlated with lymph node metastasis (P=0.029), but not with TNM stage and age (P=0.194 and P=0.471)." (PMID 33469513, 2020).
osteoporosis (2 papers, 2019 to 2020). A condition of reduced bone mass, with decreased cortical thickness and a decrease in the number and size of the trabeculae of cancellous bone (but normal chemical composition), resulting in increased fracture incidence. "In a previous study, we implicated the gene ING3 by virtue of its interaction with an osteoporosis-associated SNP, and showed that this gene is required for osteoclast differentiation in an in vitro model." (PMID 32620744, 2020).
prostate adenocarcinoma (2 papers, 2017 to 2018). "A more thorough analysis of The Cancer Genome Atlas (TCGA) database showed that an increased copy number of ING3 correlates with development of prostate adenocarcinoma." (PMID 29381681, 2018). "Correlation analysis using The Cancer Genome Atlas (TCGA) prostate adenocarcinoma cohort data (n = 498) indicated that ING3 and AR mRNA levels were positively correlated." (PMID 28511652, 2017).
leukemia (1 paper, 2010). A malignant (clonal) hematologic disorder, involving hematopoietic stem cells and characterized by the presence of primitive or atypical myeloid or lymphoid cells in the bone marrow and the blood.
lung carcinoma (1 paper, 2019). "Similar to ING2, also ING3 was expressed in some lung cancer samples but occurred most abundantly in gynecological cancer entities." (PMID 31390718, 2019). "Notably, there is very limited data available on the effect of ING3 in lung cancer, whereas the function of ING1, ING2, ING4, and ING5 has been investigated in lung cancer in more detail." (PMID 31390718, 2019). "Data specifically on the role of ING3 in lung cancer is still very limited." (PMID 31390718, 2019).
osteosarcoma (1 paper, 2018). A usually aggressive malignant bone-forming mesenchymal neoplasm, predominantly affecting adolescents and young adults.
periodontitis (1 paper, 2015). An acute or chronic inflammatory process that affects the tissues that surround and support the teeth. "EST1, MTSS1, ING3, CCND2 and SYNE2, as well as their corresponding miRNAs, might be potential therapeutic targets for periodontitis." (PMID 26705104, 2015). "CD24, EST1, MTSS1, ING3, CCND2 and SYNE2 may have the potential to be used as targets for periodontitis diagnosis and treatment.; however, more research is still needed to validate our findings." (PMID 26705104, 2015).
Sepsis (1 paper, 2023). Sepsis is defined as life-threatening organ dysfunction caused by a dysregulated host response to infection. "Five characteristic genes—BCL2A1, CD44, ADGRG1, TGIF1, and ING3—were identified, which enabled the prediction of mortality of sepsis." (PMID 37069215, 2023).
triple-negative breast carcinoma (1 paper, 2020). An invasive breast carcinoma which is negative for expression of estrogen receptor (ER), progesterone receptor (PR), and human epidermal growth factor receptor 2 (HER2). "In HER2 positive-type and triple-negative breast cancer (TNBC) patients, it had the lower rate of nuclear ING3 with high expression than that in luminal-type." (PMID 33469513, 2020).
tumor (23 papers, 2003 to 2025). "Conversely, the cytoplasmic levels of ING3 have been elevated in tumor samples in association with lymph node metastasis and the expression of 14-3-3η." (PMID 35804879, 2022). "In contrast, ING3 translocation into cytoplasm induces tumorigenesis and is associated with tumour progression in head and neck squamous cell carcinoma." (PMID 34685579, 2021). "Hypothetically, the tumour suppressor activity of ING3 in other cancer types may derive from splice variants as well." (PMID 34439818, 2021). "One possibility is that the tumour suppressor activity of ING3 in other cancer types may derive from splice variants." (PMID 34439818, 2021). "ING3 is still referred to as a candidate tumour suppressor based on initial studies performed in cancer cell lines and immunohistochemistry in normal and cancer tissues." (PMID 40149370, 2025). "Further, ING3 knockout and gain-of-function studies in mice in combination with loss of PTEN and a third hit will clarify its tumour suppressor and/or oncogenic function." (PMID 40149370, 2025). "As a crucial inhibitor of the growth gene family, ING3 is usually abnormally expressed in both the cytoplasm and nucleus of tumour cells and has been shown to be involved in the progression of many tumours." (PMID 35845928, 2022). "ING3 was reported to act as a tumor suppressor in many different cancer types to regulate apoptosis." (PMID 35804879, 2022). "In line with this, ING3 was reported to have a tumour suppressive function in many different cancer types." (PMID 34439818, 2021). "Inhibitor of growth 3 (ING3) is one of five members of the ING tumour suppressor family, characterized by a highly conserved plant homeodomain (PHD) as a reader of the histone mark H3K4me3." (PMID 34439818, 2021). "ING3 was reported to act as a tumour suppressor in many different cancer types to regulate apoptosis." (PMID 34439818, 2021). "Analysis of full-length ING3 expression levels suggests a slight upregulation in tumour samples compared with non-tumour samples." (PMID 34439818, 2021). "This suggests that the expression of ING3 is closely related to the staging and differentiation of the tumor." (PMID 33469513, 2020). "The ING3 candidate tumour suppressor belongs to a family of histone modifying proteins involved in regulating cell proliferation, senescence, apoptosis, chromatin remodeling, and DNA repair." (PMID 31905726, 2019). "We here show that loss of ING3 expression in an insertional mutant mouse model of Ing3, a candidate tumour suppressor of the ING family, leads to severe growth restriction and embryonic death latest at E11.5." (PMID 31905726, 2019). "The tumour suppressor roles of ING1 and ING2 have been well established whereas candidate tumour suppressor status remains for ING3, ING4, and ING5." (PMID 31905726, 2019). "Mapping the integration site of the UbC-mCherry cassette to the locus of the tumour suppressor candidate ING3 prompted us to further investigate the homozygous lethal phenotype." (PMID 31905726, 2019). "Our investigations create a shift in the prevailing view that ING proteins are tumour suppressors and redefine ING3 as an oncoprotein." (PMID 29381681, 2018). "Our data from cell line models showing the requirement of ING3 for the proliferation of cancer cells are also in agreement with the elevated levels of ING3 in a subset of tumours in cancer patients." (PMID 29381681, 2018). "Together, our results reveal the molecular mechanism of H3K4me3 selection by the ING3PHD and suggest that this interaction is important for mediating ING3 tumor suppressive activities." (PMID 27281824, 2016). "ING3, which is an important subunit of the human NuA4 histone acetyltransferase complex and can recognize H3K4me3, is mainly known as a tumor suppressor gene." (PMID 24066152, 2013). "Mechanistically, wild-type ING3 could exert tumour-suppressive functions in the nucleus via chromatin-dependent induction of EMT-suppressive genes." (PMID 40149370, 2025).
tumor (continued). "Another possibility is that ING3 in PCa has a tumour suppressive function specifically for EMT." (PMID 34439818, 2021). "Overexpression-based studies and sequence similarities to the tumour-suppressor ING1 led to the hypothesis that ING3 may be a tumour suppressor." (PMID 29381681, 2018). "This set of results suggests that ING3 could serve as a novel prognostic factor in PC pathophysiology to help predict the aggressiveness of the tumor, which should reduce the rate of overdiagnosis in this patient population." (PMID 28511652, 2017). "In contrast to previous studies in other tumor types where ING3 was reported to function as a tumor suppressor, we find that ING3 levels are higher in aggressive PCs, and that a high level of ING3 is a prognostic factor predicting poorer survival in patients with low AR levels." (PMID 28511652, 2017). "This suggests that ING3 may suppress tumor formation in some cases while promoting cancer in others." (PMID 27281824, 2016). "Hence, tumour suppression of ING3 is presumably based on reducing metastatic potential." (PMID 34439818, 2021). "On the other hand, ING3 may function as a tumour suppressor by inhibiting EMT induction." (PMID 34439818, 2021). "Because the ING3 protein is a known tumor suppressor that is down-regulated in multiple cancers, we searched the cBioPortal for Cancer Genomics to see whether any mutations in the PHD finger of ING3 have been reported in cancer patients." (PMID 27281824, 2016). "The inhibitor of growth 3 (ING3) belongs to a family of tumour suppressors encompassing five members (ING1–5), with the candidate tumour suppressor ING3 being the most evolutionarily distinctive." (PMID 40149370, 2025). "The ING family of tumor suppressors includes ING1–5, with the first identification of ING3 guiding the discovery of ING1–2 and 4–5." (PMID 35350574, 2022). "Analogous to ING3 in PC, ING4 splicing isoforms, missing the full nuclear localization sequence (NLS) (ING4_v2 and ING4_v4), lose tumour suppressive effects, which is rather a characteristic for full-length ING4 (ING4_v1)." (PMID 34685579, 2021). "ING3 belongs to the ING family, which act as tumour suppressors, binding to the epigenetic histone mark of methylated histone H3 lysine 4 with their highly conserved PHD." (PMID 34439818, 2021). "Based on demonstrated partial recombination, we conclude that in prostate tissue, Ing3 is not a gatekeeper tumour suppressor comparable to haploinsufficient Pten." (PMID 40149370, 2025). "We have not noticed any gross anatomical changes of the prostate or PIN lesion formation and concluded that ING3 is not a tumour suppressor comparable to PTEN that clearly results in visible malignant neoplastic transformation." (PMID 40149370, 2025). "In light of limited previous observations and recent systematic approaches, it appears that ING3 is not a tumour suppressor, at least in some cancers." (PMID 33925563, 2021). "Considering the tumour suppressor candidate status of ING3, we have not seen any abnormal developments in ING3 mutant heterozygous animals compared to wild type mice." (PMID 31905726, 2019). "Our data strikingly indicate that ING3 does not behave as a tumour suppressor but rather as an oncoprotein." (PMID 29381681, 2018). "Due to the embryonic lethal phenotype of homozygous embryos, the tumour suppressor status of ING3 during the postnatal period could not be strengthened or weakened." (PMID 31905726, 2019). "However, because of the embryonic lethal phenotype, it could not be concluded that ING3 functions as an oncoprotein or a tumour suppressor." (PMID 33925563, 2021).
tumor (continued). "For the candidate tumour suppressor genes ING3 and ING5, no mutant mouse models have been described so far to support or weaken their tumour suppressor gene status and to further investigate their function in vivo." (PMID 31905726, 2019).